TMEM14A (transmembrane protein 14A)
Description:
Inhibits apoptosis via negative regulation of the mitochondrial outer membrane permeabilization involved in apoptotic signaling pathway.
Synonyms: C6orf73; PTD011
Tractability: Antibody: UniProt predicts a signal peptide or a membrane-spanning region.
Gene: Protein-coding gene on chromosome 6 (52,671,072 to 52,686,592, forward strand). Ensembl gene ENSG00000096092.
Subcellular location: Mitochondrion membrane; Endoplasmic reticulum membrane
Subcellular location (Human Protein Atlas): Endoplasmic reticulum; Nucleoplasm
Gene Ontology:
Molecular function: protein binding
Biological process: negative regulation of apoptotic process; negative regulation of mitochondrial outer membrane permeabilization involved in apoptotic signaling pathway
Cellular component: endoplasmic reticulum membrane; mitochondrial membrane; membrane
Genetic constraint (gnomAD): Loss-of-function variants: 8 observed, 12.2 expected, observed/expected ratio (o/e) 0.66, 90% interval 0.38 to 1.18. The upper end of that interval is the gene's LOEUF score, 1.18, which puts it in group 5 of 6, group 1 being the genes least tolerant of losing a copy. Missense variants: 108 observed, 128.49 expected, observed/expected ratio (o/e) 0.84, 90% interval 0.72 to 0.99. Synonymous variants: 34 observed, 48.1 expected, observed/expected ratio (o/e) 0.71, 90% interval 0.54 to 0.94.
Homologues: Orthologues: chimpanzee TMEM14A (100% identical), dog TMEM14A (95% identical), pig TMEM14A (95% identical), rat Tmem14a (94% identical), macaque TMEM14A (91% identical), guinea pig TMEM14A (90% identical), mouse Tmem14a (85% identical), tropical clawed frog tmem14a (66% identical), zebrafish tmem14a (49% identical). Paralogues in human: TMEM14C (54% identical), TMEM14B (45% identical).
Diseases named in the same sentence as TMEM14A in open-access papers:
TMEM14A is named in the same sentence as 19 diseases in open-access papers, as found by Europe PMC text mining. Sharing a sentence is not in itself a finding about the gene and the disease. The quoted sentences say what the papers report.
ovarian carcinoma (6 papers, 2018 to 2023). A malignant neoplasm originating from the surface ovarian epithelium. "High TMEM14A expression was positively associated with tumor size, tumor stage and recurrence of ovarian cancer cells." (PMID 37367036, 2023). "Therefore, TMEM14A could provide both diagnostic and prognostic biomarkers for the early detection of ovarian cancer." (PMID 37367036, 2023). "TMEM14A was highly expressed in tumor tissues and correlated with poor prognosis in patients with ovarian cancer." (PMID 37367036, 2023). "TMEM14A up regulation also increased the cell invasive ability of ovarian cancer cells highlighting a potential role of this protein to promote metastasis." (PMID 30574087, 2018). "In the context of ovarian cancer, TMEM14A is involved in cell proliferation as shown by a cell cycle arrest when TMEM14A was invalidated in two ovarian cancer cell lines, A2780 and HO-8910." (PMID 30574087, 2018). "TMEM48 is such an example for lung cancer, TMEM14A for ovarian cancer and TMEM45B for lung and pancreatic cancers." (PMID 30574087, 2018). "Knockdown of TMEM14A in ovarian cancer cell lines can affect activation of TGF‐β pathway and inhibit the proliferation of ovarian cancer cells." (PMID 36254814, 2022).
anemia (1 paper, 2015). A reduction in the number of red blood cells, the amount of hemoglobin, and/or the volume of packed red blood cells. "Whereas TMEM14C was identified to coexpress with the core machinery of heme biosynthesis and its knockdown causes anemia in zebrafish, TMEM14A was described to stabilize mitochondrial membrane potential and thereby inhibit apoptosis in a yeast system." (PMID 25646734, 2015).
colorectal adenocarcinoma (1 paper, 2021). The most common type of colorectal carcinoma. "Differential gene expression analysis showed distinct gene expression patterns in GCA compared to colorectal adenocarcinoma, with a number of cancer-related differentially expressed genes, including upregulation of TMEM14A, GOLT1A, DSCC1, and HSD17B8, and downregulation of KCNQ1OT1 and MXRA5." (PMID 34804955, 2021).
diabetic nephropathy (1 paper, 2023). "The difference in TMEM14A expression between DN and other investigated proteinuric renal disease warrants further exploration, specifically into TMEM14A and apoptosis in diabetic nephropathy models." (PMID 38054547, 2023). "As no increase in glomerular TMEM14A protein expressing surface area was seen in diabetic nephropathy glomeruli, insufficient prevention of apoptosis due to a pre‐existent relative lack or impairment of TMEM14A might be a factor in the development of proteinuria in these patients." (PMID 38054547, 2023). "Lastly, we show that glomerular TMEM14A protein expression is increased in various proteinuric renal diseases, but not in diabetic nephropathy." (PMID 38054547, 2023).
epilepsy (1 paper, 2025). A brain disorder characterized by episodes of abnormally increased neuronal discharge resulting in transient episodes of sensory or motor neurological dysfunction, or psychic dysfunction. "Following the analysis of rs6924849, we explored the role of TMEM14A and its potential association with epilepsy." (PMID 40507571, 2025). "In a pilocarpine-induced epilepsy mouse model, TMEM14A expression showed a dramatic increase during the acute phase (1 and 8 h post-status epilepticus), likely reflecting a compensatory response to regulate the apoptosis of neurons." (PMID 40507571, 2025). "Transcriptomic analyses showed reduced TMEM14A expression in MTLE-HS hippocampi, while mice with pilocarpine-induced epilepsy exhibited a transient increase in TMEM14A expression during the acute phase post-status epilepticus." (PMID 40507571, 2025). "Transcriptomic data from the hippocampi of MTLE-HS subjects and an epilepsy mouse model were examined to assess TMEM14A expression." (PMID 40507571, 2025).
lung carcinoma (1 paper, 2026). "Approximately 50 TMEMs have been found to be deregulated and have been studied in lung cancer; some predominantly act as tumor suppressors (e.g., TMEM100 and TMEM196), while others function as oncogenes (e.g., TMEM14A and TMEM158)." (PMID 41596760, 2026).
tumor (6 papers, 2014 to 2026). "The genes with the highest influence are the transmembrane protein TMEM14A in the untreated tumor samples, the zinc-finger transcription factor ZFHX4 following 14 days of letrozole treatment, and the redox protein CYB5R3 following 90 days of letrozole treatment." (PMID 24495353, 2014). "Some of TMEM proteins act as tumor suppressors such as TMEM7, TMEM25, TMEM97, and TMEM176A; while a large number of them act as oncogenes such as TMEM14A and TMEM158." (PMID 37335919, 2023). "Furthermore, some of these proteins act as tumor suppressors (e.g., TMEM25, TMEM7) while others act as pro-oncogenes (e.g., TMEM158, TMEM14A)." (PMID 38974022, 2024).
cancer (3 papers, 2014 to 2026). A tumor composed of atypical neoplastic, often pleomorphic cells that invade other tissues. "For example, TMEM14A, coding for a transmembrane protein, was shown to be abnormally expressed in various cancers." (PMID 34804955, 2021). "TMEM14A may also play a role in the regulation of planar cell polarity by trafficking planar cell polarity proteins to the membrane including VANGL2, a protein that promotes migration and invasion in human cancer cells." (PMID 24495353, 2014).
neurological disorders (1 paper, 2025). "However, the specific role of TMEM14A in brain tissue and neurological disorders remains poorly understood." (PMID 40507571, 2025).
TMEM14A also shares sentences with these, for which no sentence is quoted: breast carcinoma (1 paper); gastric cancer (1); glioma (1); IgA nephropathy (1); lupus nephritis (1); minimal change disease (1); pancreatic cancer (1); renal disease (1); status epilepticus (1); temporal lobe epilepsy (1).